IL4 (interleukin 4)
Diseases named in the same sentence as IL4 in open-access papers (continued):
Sharing a sentence is not in itself a finding about the gene and the disease.
COVID-19 (continued). "The low levels of IL12 are comparable to healthy controls in severe COVID-19 patients, while the levels of IL4 are significantly higher in severe patients." (PMID 34571891, 2021). "The levels of IFN-γ, IL-4, IL-6, and IL-12 were significantly higher in colostrum obtained from those participants who exhibited COVID-19-related symptoms." (PMID 34382820, 2021). "Cytokine excess, in particular IL-2, IL-4, IL-6, TNF-α, and IFN-Ɣ are known drivers of the overactive inflammatory response and associated COVID-19 severity." (PMID 34675810, 2021). "Significantly higher IL-4 tissue expression and Sphingosine-1 in M2 macrophages were observed in the COVID-19 group compared to both the H1N1 and the CONTROL groups." (PMID 33122784, 2020). "The IL-4 is consistently higher in COVID-19 patients when compared to H1N1, even if considering different times from hospitalization to death." (PMID 33122784, 2020). "We first compared the levels of IFN-γ, TNF-α, IL-2, IL-4, IL-6 and IL-10 in serum samples from control group and COVID-19 patients." (PMID 32475230, 2020). "As cytokine storms played a critical role in the deterioration of COVID-19, we also detected the Th1/Th2 cytokines including IL-2, IL-4, IL-6, IL-10, TNF-α, and IFN-γ in patients infected with COVID-19." (PMID 33061829, 2020). "By morphological criteria, IL-4-expressing cells in COVID-19 patients include alveolar M2 macrophages and type II pneumocytes." (PMID 33042157, 2020). "The COVID-19 group presents statistically significant higher tissue expression of IL-4 compared to H1N1 (p = 0.003) and CONTROL groups (p = 0.05, borderline)." (PMID 33122784, 2020). "In early studies, COVID-19 was also reported to induce increased secretion of T-helper-2 (Th2) cytokines (e.g., IL4 and IL10) that suppress inflammation." (PMID 32393351, 2020). "We therefore examined the concentrations of serum cytokines, including TNF-α, IFN-γ, IL-2, IL-4, IL-6, and IL-10, from these COVID-19 patients to explore the influence of cytokine signaling." (PMID 32425950, 2020). "Concerning the inflammatory biomarkers studied, the COVID-19 group corroborates the Th2 response predominance, given the higher tissue expression of IL-4 of this group compared to H1N1 and CONTROL groups." (PMID 33122784, 2020). "In contrast, patients with COVID-19 demonstrated activation of both Th1 and Th2 immunity, culminating inexpression of IFNγ, IL-1β, IL-4, and IL-10." (PMID 32742855, 2020). "The known involvement of IL-4 in fibrotic pathways and impaired viral clearance could represent potential mechanisms linking elevated IL-4 levels with poor prognosis in COVID-19." (PMID 41217548, 2025). "The cytokine storms are characterized by significant induction of specific cytokines such as IL-6, IL-2, IL-7, GM-CSF, and IFN-γ in COVID-19 patients, which are different from other respiratory viruses with the increase in cytokines such as IL-2, IL-10, IL-4, or IL-5." (PMID 41002992, 2025). "Escalating concentrations of recombinant spike can activate human lung macrophages, triggering the production of proinflammatory cytokines that mirror the “cytokine storm” signature observed in clinical COVID-19 cases (IL-2, IL-4, IL-6, IL-1β, IL-8, IFN-γ, TNF-α, and CXCL10)." (PMID 41012643, 2025). "The higher median IgM, IgA, and IgG1 values in the sera of the MIS-C cohort to some of the COVID-19 Ags may relate to the higher type-2 cytokines (IL-4, IL-5, IL-6, and IL-13) and IL-21 enhanced Tfh activity known to promote B-cell activities." (PMID 38932242, 2024). "Out of the 17 cytokines tested, nine (IL-1β, IL-2, IL-4, IL-5, IL-12, IL-13, IL-17, granulocyte colony-stimulating factor (G-CSF), granulocyte-macrophage colony-stimulating factor (GM-CSF)) were undetectable in the peripheral blood of COVID-19 patients." (PMID 39408857, 2024). "Thus, in children with COVID-19 and appendicitis, an increase in pro-inflammatory cytokines IL-1 and IL-6, as well as anti-inflammatory cytokines IL-4 and IL-10, is observed." (PMID 38397914, 2024).
COVID-19 (continued). "When directly looking at the specific cytokines found to be able to predict the NfL levels (CRP, IL-4, IL-8, IL-9, Eotaxin, and MIP-1ß), the literature highlight that all the selected factors are highly up-regulated during COVID-19 and associated with clinical outcomes." (PMID 39125829, 2024). "The authors also investigated Th1 and Th2 cytokine dynamics in COVID-19 patients, and found that stable ratios of Th2 cytokines (IL-4, IL-6, IL-10) to IFN-γ over time indicate a dysregulated immune response, which is critical in understanding COVID-19 pathophysiology." (PMID 39518964, 2024). "However, IL-4, known for its anti-inflammatory properties, is reduced in patients who develop post-COVID-19 sequelae compared to those who fully recover." (PMID 39188722, 2024). "Plasma levels of IL-2, TNF-α, and IL-4 are elevated during the acute phase of COVID-19." (PMID 39188722, 2024). "Furthermore, in a sample of 317 patients diagnosed with COVID-19, high serum levels of IL-17 and IL-2 and low levels of IL-4 and IL-10 appeared to constitute a cytokine profile of long COVID-19." (PMID 36992491, 2023). "Furthermore, plasma IL-4 levels were found to be elevated in young, comorbidity-free COVID-19 patients in an intensive care unit." (PMID 37631998, 2023). "Furthermore, PBMCs isolated from severe COVID-19 patients at the acute phase of disease produced higher levels of IL-21, IFNγ, IL-4, and IL-17 in response to spike and RBD, than PBMCs from mild patients." (PMID 37061513, 2023). "Notably, other studies have also indicated that patients with COVID-19 have elevated levels of cytokines secreted by Th2 cells (such as IL-4 and IL-10), which inhibit the inflammatory response." (PMID 37112918, 2023). "Notably, other studies have also indicated that patients with COVID-19 have elevated levels of cytokines secreted by Th2 cells (such as IL-4 and IL-10), which normally inhibit the inflammatory response." (PMID 37112918, 2023). "Increased IL4 serum levels were associated with patients with previous infection without signs of long COVID-19, but also with lung tissue samples from COVID-19 patients who did not survive the infection." (PMID 37795240, 2023). "Therefore, it is possible to speculate that a genetic asset that favors high IL-4 production may have different pleiotropic effects, such as favoring immunoglobulin production after vaccine immune stimulation or, conversely, being a susceptibility factor for COVID-19 in vaccinated subjects." (PMID 36851291, 2023). "Furthermore, high serum levels of IL-17 and IL-2 and low levels of IL-4 appear to constitute a long-term profile of COVID-19 cytokines, and these markers are potential targets for long COVID-treatment and prevention strategies." (PMID 37237560, 2023). "In addition, patients who developed COVID-19 while prescribed Dupilumab, a monoclonal antibody that blocks IL-4 and IL-13 signaling, have been shown to have a less severe disease course." (PMID 37568438, 2023). "Interestingly, a series of COVID-19 related pathways were significantly enriched by RNAenrich, e.g. human interleukin-4 and interleukin-13 signaling (P = 5.74E-14) (P refers to P.adjust), interleukin-6 signaling (P = 8.64E-04), and so on." (PMID 37399102, 2023). "Removing ICAM-1 in the Common Cold cocktail and adding sACE2 resulted in COVID-19 Cocktail A. Removing sIL-4Rα from Cocktail A and adding IL-4 and IL-13 made Cocktail B, whereas adding IL-4 to Cocktail A gave Cocktail C. Adding IL-13 to Cocktail C gave Cocktail D." (PMID 37040185, 2023). "The tissue expressions of IL-4 and sphingosine-1, a marker for M2 subtype macrophages, were found to be significantly increased in post-mortem lungs from COVID-19 patients compared with those from patients infected with influenza virus and those of control patients." (PMID 37631998, 2023). "However, evaluating the immunoexpression of CCR4, IL-4, Sphingosine-1 and Arginase, it is deduced that the COVID-19 group had the Th2 pathway activated." (PMID 36430210, 2022).
COVID-19 (continued). "In our COVID-19 cohort, we observed increased levels of IL-2, IL-4, IL-15, IL17, and IP-10, which likely activate both T-helper-1 (Th1) and T-helper-2 (Th2) cells and lead to lung inflammation and damage, similar to what has been reported in SARS-CoV and MERS-CoV infections." (PMID 36423162, 2022). "Moreover, we observed that proinflammatory cytokines involved in lymphocyte and macrophage activation (IL-1β, IL-6, IL-16), Th2 (IL-4), and Th17 (IL-17A) responses were also increased in urine samples of COVID-19 patients." (PMID 36359444, 2022). "Interestingly, we also found the highest concentration of IL-4 in the P-COVID-19+ and reached a statistically significant difference with P-COVID-19+ (p = 0.025) and P-COVID-19- (p = 0.012)." (PMID 35901034, 2022). "It has been shown that COVID-19 subjects present elevated Th2-cytokines (IL-4 or IL-10), which could inhibit the Th1 response." (PMID 34967260, 2022). "Accordingly, we evaluated the levels of IL-17, IFN-γ, TNF-α, IL-10, IL-6, IL-4 and IL-2 in patients with clinical COVID-19 and long COVID-19, with cases classified as mild, moderate and severe, and associations with risk factors for sex, age and presence of comorbidities." (PMID 35846757, 2022). "Ultimately, pathway enrichment analysis (PEA) and Reactome mining results revealed that philanthotoxin could prevent severe lung injury in COVID-19 patients through the remodeling of interleukins (IL-4 and IL-13) and the matrix metalloproteinases (MMPs)." (PMID 35215266, 2022). "In addition, we found that cytokines related to TH2 regulations (IL-4, IL-13, IL-33), cell metabolism (lep, lep-R) and interferons (IFNα, IFNβ, IFNγ) were also predictive of life-threatening COVID-19." (PMID 35386702, 2022). "In addition, plasma concentrations of Th2 cytokines IL-4, IL-10 and IL-13 were also significantly upregulated in COVID-19 patients." (PMID 36307516, 2022). "Furthermore, high serum levels of IL-17 and IL-2 and low levels of IL-4 and IL-10 appear to constitute a cytokine profile of long COVID-19, and these markers are potential targets for COVID-19 treatment and prevention strategies." (PMID 35846757, 2022). "In recently infected persons (mean 29.8 days after COVID-19 symptom onset), we confirm a Th1 bias (and a novel IL-4-producing population of unclear significance) by flow cytometry, which does not correlate to antibody responses against the receptor binding domain." (PMID 35273611, 2022). "In addition, we also addressed the role of COVID-19 superinfection-associated cytokines such as TNF-α, IFN-γ and IL-4, which synergistically mediate impaired antibacterial effector function in myeloid immune cells." (PMID 35007290, 2022). "Cytokine storm of interleukin (IL)-2, IL-4, tumor necrosis factor-alpha (TNF-α), interferon-gamma (IFN-γ), and C-reactive protein has not been directly associated with COVID-19, whereas IL-6 and IL-10 were found to be COVID-19 severity predictors." (PMID 35054524, 2022). "When analysis was performed using the O’Brien method and the functional groupings described in the Methods, we found that groups related to TH2 regulations (IL-4, IL-13, IL-33), cell metabolism (lep, lep-R) and interferons (IFNα, IFNβ, IFNγ) were also predictive of life-threatening COVID-19." (PMID 35386702, 2022). "IL-4 production is observed in trials as mentioned following COVID-19 vaccination, whereas data about IL-17 and IL-21 which are viewed as the protective factor of vaccine-induced immunity, are still missing in patients developing pemphigus following COVID-19 vaccine administration." (PMID 35887732, 2022). "However, the opposite effect, namely decreased levels of IL-4, IL-6, IL-8, IL-10 and IL-17, were observed in convalescent patients after moderate/severe COVID-19, compared to mild convalescents and healthy controls." (PMID 35757700, 2022). "Patients with COVID-19 have shown an elevated level of IL-4." (PMID 35782361, 2022).
COVID-19 (continued). "COVID-19 group demonstrated significantly increased tissue immunoexpression of Arginase-1 and IL-4 (p = 0.002 and p < 0.0001, respectively) and increased number of Perforin-1+ (p = 0.009), CD4+ (p = 0.009), CD68+ (p = 0.013), CD138+ (p < 0.0001) cells in comparison to the H1N1 group." (PMID 36430210, 2022). "Furthermore, data from COVID-19 patients indicated high circulating levels of IL-10 and IL-4, which are protective against inflammation." (PMID 36554094, 2022). "Studies have shown that severe COVID-19 is accompanied by hypercytokinemia with high levels of pro-inflammatory cytokines such as IL-6 and IL-1β as well as anti-inflammatory cytokines such as IL-4 and IL-10." (PMID 35007290, 2022). "Interestingly, the Th2 anti-inflammatory cytokine—IL-4, which is released during COVID-19 cytokine storm, in addition to its ability to activate astrocytes, appears to have the ability to potentiate IFN-γ-mediated microglial IDO activation." (PMID 36294388, 2022). "TNF-α, IFN-γ, IL-6, IL-8, IL-4, and IL-10 were dramatically elevated in COVID-19 patients." (PMID 34646834, 2021). "The interrelationship of immune cells in COVID-19 was intrinsically identified, whereby T cells secreting IL-2, IL-4, and IL-17A were enriched among CD28+ and CD57− cells and cells secreting perforin/granzyme B/IFN-γ/tumor necrosis factor alpha (TNF-α)-expressed markers of terminal differentiation." (PMID 34488453, 2021). "Plasma cytokine IL-4 was increased in all COVID-19 participants." (PMID 33668514, 2021). "Patients with COVID-19 have elevated levels of various cytokines such as IL-2, IL-4, IL-6, and IL-10, TNF-α, IFN-γ and may present with the so-called cytokine storm." (PMID 34684384, 2021). "To functionally test the role of cytokines on the viability of lymphocytes, we treated PBMCs isolated from healthy donors with selected groups of cytokines (e.g., IL-10, IL-15, IL-18, IL-8, IL-6, IL-1RA, IL-2RA, IL-4) for 36 h, using the maximum doses detected in COVID-19 serum." (PMID 34103487, 2021). "Based on our results and these previous studies, we speculate that IL-2, IL-4, and INF-γ are involved in the infiltration of alveolar inflammatory cells and lung injury caused by COVID-19." (PMID 33967617, 2021). "In addition, patients who acquired COVID-19 while prescribed Dupilumab, a mAb that blocks IL-13 and IL-4 signaling, had less severe disease." (PMID 34185704, 2021). "In addition, critically ill COVID-19 patients had significantly higher levels of IL-2, IL-4, and INF-γ than those with moderate or severe disease 33, 34, and those with severe COVID-19 had higher levels of certain cytokines than those with mild disease." (PMID 33967617, 2021). "This lends support to our findings that Streptococcus sanguinis SK1 = NCTC 7863 may influence the immune response to COVID-19 by upregulating inflammatory IL-6 signaling and downregulating IL-4 signaling." (PMID 34200572, 2021). "The kinetics of IL-4 are different in COVID-19 patients with different illness severity." (PMID 35126355, 2021). "All things considered, it is reasonable to postulate that an increase of IL-4 levels may play an important role in the convalescence of COVID-19 through either T cells, B cells, or other type 2 immunity-associated cells, such as macrophages." (PMID 34307393, 2021). "IL-4 continued to be significantly elevated in all COVID-19 participants." (PMID 33668514, 2021). "Interestingly, in this study, an increased number of IL-4-expressing cells were found in the alveolar septa of severe COVID-19 patients." (PMID 34685733, 2021). "However, we observed that severe COVID-19 patients display strongly up-regulated IL-4 production in both CD4+ and CD8+T cells." (PMID 33692788, 2021). "Similarly, IL-4 and IL-10 were found to be increased in response to antigenic stimulation especially in the products of COVID-19 recovered individuals." (PMID 35003063, 2021).
COVID-19 (continued). "Of note, the higher levels of Th2 cytokines, particularly IL-4 and IL-5, might inhibit Th1 protective antiviral responses in COVID-19 patients." (PMID 33995342, 2021). "The observed elevation of IL-4 might suggest that there is a differential set of regulatory T cell and B cell immune responses occurring in early convalescence of COVID-19 patients." (PMID 34307393, 2021). "Due to the elevated levels of IL-2R and IL-6 accompanied by the advancement of COVID-19, several cytokines secreted by T helper type 2 (Th2) cells that could neutralize the inflammatory responses including IL-4 and IL-10." (PMID 32822430, 2020). "Therefore, it is worth considering PBMT in COVID-19 as a useful tool in regulating IL-4 and IL-10 which correlate with Th-2 response." (PMID 32947974, 2020). "Even though inflammatory cytokine storms were thought to be a mechanism for COVID-19 progression, there was only an increase in IL-2, IL-4, IL-6, IL-10, TNF-α, and IFN-γ when comparing pneumonia patients with healthy people, but no significant increase in severe patients compared to mild patients." (PMID 32985562, 2020). "Interestingly, the production of cytokines by CD4+ (mainly IL-2 and IFN-γ and trace amounts of IL-4, IL-5, IL-13, or IL-17α) was also reported in COVID-19 convalescents." (PMID 32916812, 2020). "In the cluster of cytokine signaling, IL-1 and IL-6 signaling pathways were negatively correlated, while IL-4 and IL-12 signaling pathways were positively correlated, shows that IL-4 and IL-12 have more significant effects on COVID-19 lung tissue than other cytokines." (PMID 33264345, 2020). "However, in COVID-19, IL-4 may enhance immune response by promoting the secretion of inflammatory factors, helping the body resist the virus, indicating that it may have a pro-inflammatory effect during the acute infection stage." (PMID 40495223, 2025). "Unlike PTB, extraPTB-COVID-19 is less likely to cause severe pulmonary complications, though it may lead to increased systemic inflammation due to IL-10 and IL-4 upregulation." (PMID 40283612, 2025). "Thus, in the context of COVID-19, IL-4 and IL-5 may contribute to enhancing humoral immunity, promoting the generation of antibodies that target the SARS-CoV-2 virus." (PMID 40910046, 2025). "Except for IL-8 decreased in the second trimester after infected with SARS-CoV-2, IL-2, TNF-α, TNF-β, IFN-γ, IL-4, IL-5, IL-6, IL-10, IL-17A, IL-17F, IL-22, IL-1β and IL-12p70 didn't change in the three trimesters between healthy pregnancies and pregnant women with COVID-19." (PMID 39113896, 2024). "This variant was not previously reported in relation to COVID-19; however, IL4 has been studied regarding susceptibility to SARS-CoV infection, and it was found that its protein product downregulates cell surface expression of ACE2, therefore inhibiting SARS-CoV replication." (PMID 37795240, 2023). "However, type 2 cytokines, IL-4 and IL-13, are also a key factor in promoting and aggravating COVID-19, and expressions of IL-4 and IL-13 are elevated in the serum of patients with COVID-19." (PMID 37240520, 2023). "Based on the results of the in vivo COVID-19 cytokine storm study, we focused on the IL-1β, IL-2, IL-6, TNFα, IL-4, and IL-10 molecular pathways as the key elements of the inflammatory response in order to identify the molecular mechanisms of peptidergic regulation of the cytokine storm in COVID-19." (PMID 37686182, 2023). "In addition, TGFβ1, TGFβ3, IL-6, and IL-10 may be influential biomarkers of COVID-19 severity during the early phase of infection, whereas Th2 cytokines, IL-4 and IL-13, may be markers of persisting severity." (PMID 37569646, 2023). "The results obtained from PEA analysis combined Reactome-mining presented an interesting primary role of philanthotoxin in remodeling the interleukins (especially IL-4, IL -13) and matrix metalloproteinases (MMPs), which could alleviate lung injury in COVID-19 patients." (PMID 35215266, 2022).